MZT2B (mitotic spindle organizing protein 2B)
Description:
Required for the recruitment and the assembly of the gamma-tubulin ring complex (gTuRC) at the centrosome. The gTuRC regulates the minus-end nucleation of alpha-beta tubulin heterodimers that grow into microtubule protafilaments, a critical step in centrosome duplication and spindle formation.
Synonyms: FAM128B; MOZART2B; FLJ14346
Tractability: PROTAC: ubiquitination databases record sites on it.
Gene: Protein-coding gene on chromosome 2 (130,181,737 to 130,190,729, forward strand). Ensembl gene ENSG00000152082.
Subcellular location: Cytoplasm, cytoskeleton, microtubule organizing center, centrosome; Cytoplasm, cytoskeleton, spindle
Subcellular location (Human Protein Atlas): Centrosome; Cytosol; Nucleoplasm
Pathways (Reactome):
Cell Cycle: Recruitment of NuMA to mitotic centrosomes; Recruitment of mitotic centrosome proteins and complexes
Gene Ontology:
Molecular function: protein binding
Biological process: microtubule nucleation
Cellular component: centrosome; gamma-tubulin ring complex; spindle; cytosol; gamma-tubulin complex
Genetic constraint (gnomAD): Loss-of-function variants: 9 observed, 7.58 expected, observed/expected ratio (o/e) 1.19, 90% interval 0.71 to 1.84. That is too few expected variants to judge how well the gene tolerates losing a copy. Missense variants: 207 observed, 181.21 expected, observed/expected ratio (o/e) 1.14, 90% interval 1.02 to 1.28. Synonymous variants: 85 observed, 82.28 expected, observed/expected ratio (o/e) 1.03, 90% interval 0.87 to 1.24.
Homologues: Orthologues: chimpanzee MZT2A (99% identical), macaque MZT2B (96% identical), dog MZT2B (92% identical), mouse Mzt2 (70% identical), rat Mzt2b (69% identical), tropical clawed frog mzt2b (51% identical), zebrafish mzt2b (47% identical). Paralogues in human: MZT2A (96% identical).
Diseases named in the same sentence as MZT2B in open-access papers:
MZT2B is named in the same sentence as 7 diseases in open-access papers, as found by Europe PMC text mining. Sharing a sentence is not in itself a finding about the gene and the disease. The quoted sentences say what the papers report.
breast carcinoma (2 papers, 2020 to 2025). "Conversely, the tumor suppressor Matrin3 (MATR3) inhibited breast cancer growth by suppressing MZT2B expression (10.1158/1538-7445.SABCS20-PS19-14)." (PMID 41213905, 2025). "MZT2B is also overexpressed in breast cancer, where its knockdown or knockout significantly decreased cell viability, migration, and invasion." (PMID 41213905, 2025). "To date, only one study has identified MZT2B as a target for MYC in gene expression data for breast cancer cell lines and tissues." (PMID 33351778, 2020).
gastric cancer (2 papers, 2020 to 2024). A primary or metastatic malignant neoplasm involving the stomach. "Its paralog MZT2B (~96% identity), is overexpressed in patients with gastric cancer." (PMID 39409043, 2024).
Alzheimer disease (1 paper, 2022). A progressive, neurodegenerative disease characterized by loss of function and death of nerve cells in several areas of the brain leading to loss of cognitive function such as memory and language. "MZT2B has been reported to be one of the potential hippocampus genes associated with Alzheimer’s disease." (PMID 36011399, 2022).
meningioma (1 paper, 2021). A generally slow growing tumor attached to the dura mater. "Among 32 key hub genes screened, EPN1, EXOSC4, H2AX, and MZT2B not only showed significant differences between meningioma molecular subtypes but also had the potential to be the marker genes of specific meningioma subtype." (PMID 35004283, 2021). "EPN1, EXOSC4, H2AX, and MZT2B not only showed significant differences between meningioma molecular subtypes but also had the potential to be the marker genes of specific meningioma subtypes." (PMID 35004283, 2021). "The expression of EPN1, EXOSC4, H2AX, and MZT2B was related to both WHO grades and age of patients and was significantly different between normal meningeal tissues and meningiomas." (PMID 35004283, 2021).
Pleural effusion (1 paper, 2025). The presence of an excessive amount of fluid in the pleural cavity. "Single-cell RNA sequencing analysis confirmed predominant MZT2B enrichment within malignant epithelial cells, particularly in proliferating carcinoma subsets, across primary tumors and metastatic sites (brain, lymph node, pleural effusions)." (PMID 41213905, 2025).
tumor (2 papers, 2020 to 2025). "Analysis of LUAD brain metastatic lesions (mBrain) similarly demonstrated a pronounced upregulation of MZT2B within the malignant epithelial cell clusters, consistent with its elevated expression in primary tumor epithelial cells." (PMID 41213905, 2025). "These in vitro findings were powerfully corroborated by in vivo studies, where MZT2B knockdown markedly impaired NSCLC tumor growth in subcutaneous xenograft models, confirming its crucial role in tumor progression." (PMID 41213905, 2025). "Conversely, MZT2B expression remained minimal in the epithelial cells of normal lung tissues, underscoring its tumor-specific enrichment." (PMID 41213905, 2025). "qRT-PCR assays unequivocally demonstrated a significant upregulation of MZT2B mRNA transcript levels within the malignant tumor tissues when compared to their matched normal counterparts." (PMID 41213905, 2025). "In vivo studies using subcutaneous xenograft models confirmed that MZT2B knockdown markedly impaired NSCLC tumor growth, reduced proliferation, increased apoptosis, downregulated COX5B expression and diminished mitochondrial function." (PMID 41213905, 2025). "This upregulation was particularly evident in paired tumor samples, where MZT2B expression was markedly increased compared to adjacent normal tissues in both LUAD and LUSC." (PMID 41213905, 2025). "These in vivo results strongly support that MZT2B is a critical regulator of NSCLC tumor growth, largely mediated through its impact on mitochondrial function and cellular metabolism." (PMID 41213905, 2025). "Complementary Western blot analyses, exemplified by four individual patient pairs, consistently revealed higher MZT2B protein expression in the tumor specimens, providing initial evidence of concordant protein upregulation." (PMID 41213905, 2025). "MZT2B was most expressed in intestinal GC tumor samples [mRNA median (IQR): 1.43 (0.51); protein median (IQR): 1.52 (0.45); p <0.001]." (PMID 33351778, 2020). "Thus, the substantial reduction in tumor burden highlights the crucial role of MZT2B in NSCLC tumor growth in vivo." (PMID 41213905, 2025). "Likewise, we identified an increase in mRNA and protein levels in tumor samples from 110 patients with intestinal GC (M1), for MZT2B and CDC16 (p <0.001 for all analyzes)." (PMID 33351778, 2020). "MZT2B critically drives NSCLC cell proliferation, survival, migration, and tumor growth possibly by maintaining mitochondrial function and respiration, potentially through the regulation of COX5B." (PMID 41213905, 2025). "In this work, qPCR and western blot results revealed a significant increase in expression levels of TTLL12, MZT2B, CDC16 and UBE2T in GC tumor samples of diffuse and intestinal-type, when compared with normal gastric tissues." (PMID 33351778, 2020). "Quantitative assessment of immunoblots across the entire patient cohort (n = 20) further corroborated a significant elevation of MZT2B protein abundance in NSCLC tumor tissues relative to the adjacent non-malignant controls." (PMID 41213905, 2025).
cancer (1 paper, 2025). A tumor composed of atypical neoplastic, often pleomorphic cells that invade other tissues. "Intriguingly, increasing glucose concentration (Glu) in the cell culture media of kdMZT2B-sh2 pNSCLC1 cells significantly suppressed the anti-cancer effects induced by MZT2B knockdown." (PMID 41213905, 2025). "Employing an unbiased approach, we first analyzed single-cell RNA sequencing data from cancer cell subpopulations to identify the top 100 genes positively correlated with MZT2B expression (termed COR-scRNA)." (PMID 41213905, 2025). "Quantitative analysis further revealed a substantial upregulation of MZT2B within these cancer cell aggregates, with a particularly increased expression observed in LUSC compared to LUAD." (PMID 41213905, 2025). "This refined segmentation corroborated the elevated MZT2B expression within these sub-clusters, exhibiting significant enrichment within proliferating carcinoma cell subsets." (PMID 41213905, 2025). "Despite the growing evidence linking MZT2B to cancer, several critical research gaps remain." (PMID 41213905, 2025). "Moreover, detailed functional studies, including gain-of-function and loss-of-function experiments, are essential to rigorously validate MZT2B’s oncogenic roles in other cancer types." (PMID 41213905, 2025). "This suggests that MZT2B promotes NSCLC malignancy, at least in part, by orchestrating mitochondrial function through its regulation of COX5B, thereby supporting the heightened metabolic demands of cancer cells." (PMID 41213905, 2025).